MMP21 (matrix metallopeptidase 21)
Description:
Plays a specialized role in the generation of left-right asymmetry during embryogenesis. May act as a negative regulator of the NOTCH-signaling pathway. Cleaves alpha-1-antitrypsin.
Synonyms: MMP-21; HTX7
Tractability: Small molecule: it belongs to a druggable protein family. Antibody: UniProt places it where antibodies can reach, with high confidence; UniProt predicts a signal peptide or a membrane-spanning region; its Gene Ontology location is reachable by antibodies, with medium confidence.
Gene: Protein-coding gene on chromosome 10 (125,753,580 to 125,775,913, reverse strand). Ensembl gene ENSG00000154485.
Subcellular location: Secreted
Gene Ontology:
Molecular function: metalloendopeptidase activity; metallopeptidase activity; zinc ion binding
Biological process: determination of left/right symmetry; collagen catabolic process; determination of heart left/right asymmetry; extracellular matrix organization; proteolysis
Cellular component: extracellular matrix; extracellular region
Genetic constraint (gnomAD): Loss-of-function variants: 42 observed, 44.53 expected, observed/expected ratio (o/e) 0.94, 90% interval 0.74 to 1.22. The synonymous counts are far from expectation, so gnomAD's model fits this gene poorly and the ratio says little. Missense variants: 747 observed, 699.11 expected, observed/expected ratio (o/e) 1.07, 90% interval 1 to 1.13. Synonymous variants: 341 observed, 277.9 expected, observed/expected ratio (o/e) 1.23, 90% interval 1.12 to 1.34.
Homologues: Orthologues: chimpanzee MMP21 (99% identical), macaque MMP21 (96% identical), guinea pig MMP21 (80% identical), rabbit MMP21 (78% identical), mouse Mmp21 (78% identical), rat Mmp21 (76% identical), dog MMP21 (72% identical), tropical clawed frog mmp21 (59% identical), zebrafish mmp21 (51% identical), Caenorhabditis elegans zmp-5 (22% identical). Paralogues in human: MMP17 (28% identical), MMP15 (27% identical), MMP24 (27% identical), MMP14 (26% identical), MMP16 (26% identical), MMP25 (25% identical), MMP19 (25% identical), MMP2 (25% identical), MMP28 (24% identical), MMP3 (24% identical), MMP1 (24% identical), MMP10 (24% identical), and 11 more.
Diseases named in the same sentence as MMP21 in open-access papers:
MMP21 is named in the same sentence as 23 diseases in open-access papers, as found by Europe PMC text mining. Sharing a sentence is not in itself a finding about the gene and the disease. The quoted sentences say what the papers report.
congenital heart disease (5 papers, 2020 to 2025). A heart disease that is present at birth. "Herein, we present a rare maternal origin 10q26.13q26.2 interstitial deletion unmasking a MMP21 recessive mutation in a Chinese fetus with congenital heart disease (CHD), intrauterine growth restriction (IUGR), and microcephaly." (PMID 39976347, 2025). "MMP21 biallelic variants have recently been associated with heterotaxy syndrome and congenital heart defects (CHD)." (PMID 39858609, 2025). "This study introduces a recessive MMP21 mutation unmasked by a rare 10q26.13q26.2 deletion via WES in a Chinese fetus with congenital heart disease (CHD), IUGR, and microcephaly." (PMID 39976347, 2025). "Although the majority of the progeny (93.9%; n = 132 mice) died immediately after birth, likely due to congenital heart disease caused by MMP21 abrogation, we analyzed the APCMin-Villin-RasV12-MMP21 KO mice that were born healthy, grew normally, and did not exhibit apparent diseases." (PMID 37923722, 2023). "Three MMP21 heterozygous non-synonymous variants (c.731G > A (p.G244E), c.829C > T (p.L277F), and c.1459A > G (p.K487E)) were identified in three unrelated Chinese Han patients with HTX and complex congenital heart defects." (PMID 36123719, 2022).
melanoma (2 papers, 2020 to 2022). A malignant, usually aggressive tumor composed of atypical, neoplastic melanocytes. "Moreover, analysis of the melanoma immunopeptidome led to the identification of MHC-II-bound citrullinated peptides are derived from MMP21, Cp450, and GRI proteins." (PMID 36291752, 2022).
Autosomal visceral heterotaxy 7 (1 paper, 2022). "The second involves MMP21, whose biallelic mutations cause Autosomal visceral heterotaxy 7 (MIM: #616749), that includes the transposition of the great arteries." (PMID 36360260, 2022).
Carpenter syndrome (1 paper, 2021). An extremely rare autosomal recessive syndrome characterized by premature closure of cranial sutures leading to cone-shaped head, fusion of the digits, and the presence of more digits than normal. "In each case the second variant, a heterozygous missense, was not specifically flagged, even though the patient had a very characteristic phenotype (MEGF8: Carpenter syndrome; MMP21: heterotaxy) associated with a limited number of known disease-causing genes." (PMID 34429528, 2021).
colorectal cancer (1 paper, 2023). A primary or metastatic malignant neoplasm that affects the colon or rectum. "Additionally, in this study, we observed significant upregulation of MMP21 in early human colorectal cancers, and its expression positively correlated with NF-κB signaling, Wnt signaling, and MAPK pathways." (PMID 37923722, 2023).
colorectal squamous cell carcinoma (1 paper, 2023). A very rare colorectal carcinoma characterized by the presence of a malignant squamous cell infiltrate. "MMP-21 studies show positive expression in development, stromal remodeling, and inflammation in tissue and high expression in gastric, esophageal, and colorectal squamous cell carcinomas." (PMID 36855499, 2023).
dermatofibromas (1 paper, 2019). "Moreover, MMP-21 protein was found in vivo in fibroblasts in dermatofibromas; thus, it may affect the growth pattern of these lesions." (PMID 31582779, 2019).
Dextrocardia (1 paper, 2022). The heart is located in the right hand sided hemithorax. "Additionally, three rare heterozygous non-synonymous MMP21 variants were identified in three unrelated Chinese Han patients with HTX and complex cardiac malformations: p.G244E in dextrocardia, p.L277F in dextrocardia and RAI, and p.K487E in RAI." (PMID 36123719, 2022).
esophageal cancer (1 paper, 2023). A primary or metastatic malignant neoplasm involving the esophagus. "Among the 28 known MMPs, MMP-1, MMP-2, MMP-9, MMP-10, MMP-14, and MMP-21 have been found to be closely associated with the metastasis and invasion of esophageal cancer." (PMID 37359527, 2023). "Reduced expression levels of MMP-14 inhibit infiltration and proliferation of esophageal cancer, suggesting that MMP-14 and MMP-21 can mediate immune evasion of tumor cells through specific regulatory networks." (PMID 37359527, 2023).
glioma (1 paper, 2025). A benign or malignant brain and spinal cord tumor that arises from glial cells (astrocytes, oligodendrocytes, ependymal cells). "For example, bioinformatics analyses have shown that certain MMPs, such as MMP-1, MMP-11, MMP-19, and MMP-21, are consistently upregulated in GBM compared to normal brain tissue, suggesting that they may serve as biomarkers for diagnosis and prognosis in high-grade gliomas." (PMID 40265458, 2025).
hepatocellular carcinoma (1 paper, 2020). A malignant tumor that arises from hepatocytes. "In our study, MMP21 was found to be upregulated in hepatocellular carcinoma and associated with microvascular invasion." (PMID 33100908, 2020). "We examined MMP21 expression in three kinds of hepatocellular carcinoma cells by western blot." (PMID 33100908, 2020).
liver cancer (1 paper, 2020). An epithelial or non-epithelial malignant neoplasm that arises from the liver. "Immunohistochemistry analysis showed a positive correlation between ADAM17 and MMP21 in patients with liver cancer." (PMID 33100908, 2020).
Oral Squamous Cell Carcinoma (1 paper, 2023). "The primary objective of this study was to find the expression of MMP-21 between oral squamous cell carcinoma and healthy tissue." (PMID 36855499, 2023). "In this retrospective study, banked pathology was used to observe the expression of MMP-21 in oral squamous cell carcinoma." (PMID 36855499, 2023).
situs inversus (1 paper, 2025). A congenital condition in which there is complete right-to-left reversal of the position of the major thoracic and abdominal organs (that is, they are arranged in a mirror image of the normal positioning). "Functional analysis indicated that the underlying mechanism of HTX and CHD may not be the haploinsufficiency of MMP21, although loss of function in MMP21 can cause the phenotypes of situs inversus with CHD in mice with chemically induced missense mutations c.677T>C, p.(Ile226Thr) or p.(Ala321Pro)." (PMID 39976347, 2025).
tumor (11 papers, 2009 to 2025). "Our data indicate that the expression of MMP21 is significantly higher in MHCC97H cells than in Huh7 and SMMC7721 cells, which have lower metastatic potential, suggesting that MMP21 may be associated with tumor cell metastasis." (PMID 33100908, 2020). "MMP-28 was found in tumor cells, particularly in smaller tumors (<2 cm), and in tumor stroma, MMP-21 was detected in tumor cells." (PMID 40227764, 2025). "MMPs are primarily expressed in stromal cells in vivo; the expression of MMP-21 is largely restricted to epithelium and tumor cells." (PMID 36855499, 2023). "INPP5A, HLA-G1, MMP-21, and IL-10 showed to be the most appropriate candidates to discriminate tumor/non-tumor groups due to the total AUCs of all combinations (>60%)." (PMID 36437782, 2022). "Regarding the tumor depth invasion in the esophageal wall (T staging), concomitant overexpression of HLA-G1 with IL-10 (p = 0.048) and MMP-21 (p = 0.043) was observed in ESCC patients with T3 depth of invasion." (PMID 36437782, 2022). "Positive correlations between MMP21 and tumor diameter, depth of invasion, vessel invasion,lymph node distant metastases,and tumor-node-metastasis stage were observed in gastric cancer." (PMID 33100908, 2020). "Also, the concomitant overexpression of IL-10 and MMP-21 was observed in tumor samples with stage III (p = 0.027)." (PMID 36437782, 2022). "Indeed, our finding demonstrated the significant correlation between concomitant expression of HLA-G1 and MMP-21 with the invasion of the tumor to adventitia (T3) in ESCCs." (PMID 36437782, 2022). "Overexpression of ADAM17 may improve tumor processing by cleaving the prodomain of MMP21 and activating it." (PMID 33100908, 2020). "Furthermore, MMP21 was recently shown to play an important role in tumor processing." (PMID 33100908, 2020). "In addition, the expression level of MMP-21 and -25 was very low in normal and tumor tissues." (PMID 19531263, 2009). "Previous researchers have found that MMP-21 has the capability to degrade denatured collagen, especially collagen type IV, V, VII, IX, and X; thus, MMP-21 eases tumor cells’ invasion and facilitates metastasis." (PMID 36855499, 2023). "Human matrix metalloproteinase 21 (MMP21), the newest member of the MMP gene family, has been suggested to play an important role in embryogenesis and tumor progression." (PMID 33100908, 2020). "MMP23 is a member of matrix metalloproteinase family (MMP23A, MMP21, MMP23B, MMP22) that participates in many aspects of tumour growth and metastasis." (PMID 26482227, 2015). "Furthermore, the H-score of MMP21 positively correlated with that of nuclear β-catenin, p-ERK or nuclear p65 in tumor tissues." (PMID 37923722, 2023). "The expression of MMP-21 is noticed in the invasive front of the tumor rather than the dysplastic cells." (PMID 36855499, 2023). "Moreover, we have previously provided evidence for the upregulation of MMP-21 in ESCC patients, which was correlated with advanced stages and tumor invasion depth; thus, it facilitates the aggressive pattern of these lesions." (PMID 36437782, 2022). "It has also been reported that MMP21 is expressed in cancer cells located in the invasive front of tumors rather than dysplastic cells and enhances tumor metastasis in some solid tumors." (PMID 33100908, 2020).
cancer (7 papers, 2016 to 2024). A tumor composed of atypical neoplastic, often pleomorphic cells that invade other tissues. "Besides, there were significant correlations between the concomitant expression profiles of INPP5A/HLA-G1, INPP5A/IL-10, and INPP5A/MMP-21 in the patients with invaded cancer cells into the adventitia." (PMID 36437782, 2022). "Therefore, we compared gene expression for cancer-associated fibroblast (CAF) markers including MMP2, MMP9, MMP21, TGFA, CXCL12, ITGA3, FAPα, and IL32 in fibroblasts derived from normal skin and MF tumors." (PMID 33941102, 2021). "There are at least 23 matrix metalloproteinases expressed in humans, and MMP21 and MMP26 have been reported to play an important role in the progression of several cancers, including PCa." (PMID 38240702, 2024). "Based on the integral role of each gene in different cancers, we took the opportunity to focus on novel potential regulatory crosstalk among the INPP5A, HLA-G1, IL-10, and MMP-21 in ESCC." (PMID 36437782, 2022). "Some MMPs had very high numbers of transcripts present (gene cluster A), while six MMPs in gene cluster C (MMP27, MMP21, MMP20, MMP26, MMP23A, and MMP8) featured scant numbers of transcript copies across any cancer tissue." (PMID 31200666, 2019).
MMP21 also shares sentences with these, for which no sentence is quoted: esophageal squamous cell carcinoma (2 papers); ciliopathy (1); gastric cancer (1); microcephaly (1); ovarian carcinoma (1); pancreatic cancer (1); systemic sclerosis (1).